CD34 (CD34 molecule)
Diseases named in the same sentence as CD34 in open-access papers (continued):
Sharing a sentence is not in itself a finding about the gene and the disease.
tumor (continued). "Tumor cells showed negative staining for the following markers: CD117 (n = 4), CD34 (n = 3), DOG-1 (n = 4), STAT6 (n = 2), EMA (n = 2), Desmin (n = 3), and SMA (n = 3)." (PMID 33588954, 2021). "The VM structure criteria were (a) vascular‐like channels lined with tumor cells and (b) positive for PAS but negative for CD34 (PAS + /CD34 −)." (PMID 33320958, 2021). "In an Hu-CD34+ HSC model, while partial HLA-matched PDX tumors were implanted, the tumor growth was not significantly different compared with that of non-HLA-matched NSG mice." (PMID 33996603, 2021). "Immunostaining for HepPar1, CD34, CD117 (C-kit), S100, HMB45, myogenin, ALK-1, and α-fetoprotein were found to be negative in the primary tumor cells." (PMID 34162402, 2021). "The ECs-related genes such as ANGPT2, CD34, LYVE1, VWF and PECAM1 were highly upregulated in the vascularized tumor tissue as compared to non-vascularized tissue due to the presence of BVs." (PMID 34754042, 2021). "IHC studies show the tumor cells to be positive for FLI-1 and negative for S100 protein, SOX10, desmin, myogenin, WT1, SMA, CD34 and pan-cytokeratin." (PMID 34745213, 2021). "The immunohistochemical profile showed tumor cells that express Melan-A and smooth muscle actin, while they were negative for pan-cytokeratin, PAX8, CK7, CD117 and CD34." (PMID 33344317, 2020). "Immunophenotypically, the tumor was positive for vimentin, epithelial membrane antigen (EMA) and negative for CK-pan, CAM5.2, CD31, CD34, smooth muscle actin (SMA), desmin, anaplastic lymphoma kinase (ALK), calponin, TTF-1 and S-100 protein." (PMID 32039736, 2020). "Immunohistological examination showed that the spindle-shaped tumor cells were positive for α-SMA and negative for c-kit and CD34." (PMID 33006746, 2020). "By immunohistochemistry, tumor cells demonstrated strong nuclear cyclin D1 expression and multifocal smooth muscle actin staining but were negative for MUC4, ERG, CD34, S-100 protein, desmin, STAT6, CD45, MDM2, CDK4, ALK, and ROS1." (PMID 32461620, 2020). "The tumor was negative for S100 protein, cytokeratin (CK), glial fibrillary acidic protein (GFAP), CK7, SOX10, CD31, CD34, desmin, MyoD1, myogenin, smooth muscle actin (SMA), CD117, β-catenin and MUC4." (PMID 31915021, 2020). "On immunohistochemistry (IHC), all 7 cases expressed vascular markers CD31, CD34 and ERG confirming the endothelial lineage of tumor cells and were negative for epithelial markers of CK AE1/AE3, Cam 5.2, CK7 and CK 20, Glypican3 and Hep par1." (PMID 32977811, 2020). "CD34 and VEGFR2 expression were uniformly expressed in tumor vessels and not present in other cell types within the tumor microenvironment." (PMID 32321460, 2020). "Immunohistochemical staining is required for the diagnosis of SFTP; the tumor cells are positive for STAT6, CD34, CD99, and BCL2, whereas they are negative for desmin, S-100, and alpha-SMA." (PMID 32638177, 2020). "The tumor cells were positive for Trk and SMA, but negative for S100, CD34, ALK, CD10, desmin, myogenin, CD99, CD56, CK, EMA, and STAT6." (PMID 32957984, 2020). "Upon PAS and CD34 double staining, VM channels form in straight lines, curves or branches, and only one layer of PAS-positive substances can be observed between tumor cells and the blood flow, with no surrounding endotheliocytes." (PMID 32035486, 2020). "Microvessel density (MVD/CD34) and glucose transporter −1through the cell membrane (GLUT-1) were not significantly correlated with tumour volume and grade." (PMID 30989489, 2020). "Tumor cells were immunohistologically positive for α-smooth muscle actin (α-SMA) and negative for c-kit, CD34, and the S100 protein." (PMID 33006746, 2020). "Immunohistochemically, the tumor cells are positive for CD31, ERG, FLI1, and cytokeratin (AE1/AE3), but negative for CD34." (PMID 32316685, 2020).
tumor (continued). "Although CD34 staining indicated that angiogenesis occurring in all tumors, smaller and thinner blood vessels were found in caveolin-1 siRNA-expressing SMMC7721 tumor sections compared to negative control tumors in the spleen." (PMID 32676485, 2020). "In ductal carcinoma in situ and IBC-NST, all cases were negative for CD34+ fibroblasts, while a substantial proportion exhibited α-SMA+ myofibroblasts in the tumor stroma instead." (PMID 32435886, 2020). "By immunohistochemistry, the tumor was positive for CD31, CD34, ERG, and TFE-3 and negative for PCK, CK8/18, EMA, CK19, Glypican3, hepatocytes, and arginase." (PMID 33121478, 2020). "Immunochemical studies showed that the tumor was positive for SMA and collagen type IV, and negative for C-Kit, CD34, desmin, and S100." (PMID 33270165, 2020). "Although a perfect HLA match between CD34+ HSC donor and tumor patient is impossible, a partial HLA match did not negatively affect tumor growth in recent reports on PDXs." (PMID 33364198, 2020). "Tumor cells were immunohistologically positive for α-SMA and h-caldesmon; partially positive for desmin; negative for c-kit, CD34, DOG-1, and the S-100 protein; and showed a Ki-67 labeling index of 70–80%." (PMID 33006746, 2020). "Immunohistochemical analysis showed that the tumour was positive for vimentin, CD99, Bcl-2 and CD34 and negative for D2–40, desmin, S-100, SMA and CK and the Ki-67 index was as low as 1%." (PMID 31391089, 2019). "DTs showed only a mild increase in the number of CD34-positive cells and no changes in VWF expression in comparison with PTs, which displayed a similar tumor size." (PMID 31803626, 2019). "Our patient’s tumor showed the typical staining pattern of DFSP, with positive staining for CD34 and negative staining for pankeratin, CK5/6, and S100." (PMID 31852518, 2019). "Immunohistologic analysis demonstrated the tumor cells were positive for α-smooth muscle actin, β-catenin and Vimentin, and negative for AE1/AE3, Bcl-2, CD34, CD117, Factor VIIIR Ag, S-100 protein, or STAT6." (PMID 30206803, 2019). "The tumor cells were positive for DOG1, sporadically positive for CD34 (data not shown) and CD117, and negative for S-100, Desmin, SMA, H-caldesmon, and CK-pan (data not shown)." (PMID 31647020, 2019). "We first stained the tumor tissues with vascular endothelial biomarkers CD31 and CD34; we found the expression of CD31 was not significantly different among these groups." (PMID 31312613, 2019). "The pathological findings were compatible with GIST and the tumor consisted of spindle cells with positive staining for KIT, CD34, and DOG1 and negative or weak staining for desmin and S-100 protein." (PMID 30943904, 2019). "Tumor cells were not stained for STAT6, AE1/AE3, Bcl-2, CD34, CD117, Factor VIIIR Ag, or S-100 protein (data not shown)." (PMID 30206803, 2019). "The tumor cells were positive for S-100 and negative for CD117, DOG1, CD34, Desmin, smooth muscle actin (SMA) and H-caldesmon (data not shown); the Ki-67 labeling index of the cancer cells was less than 5% (data not shown)." (PMID 31647020, 2019). "Comparing with necrosis seen on H&E, CD34 staining and VEGF staining positive expressions were mostly distributed in non-necrotic areas of the tumor." (PMID 31442259, 2019). "Immunohistochemically, tumor cells were strongly positive for CD31 and Factor VIII-related antigen, negative for CD34, weakly and focally positive for EMA and Cytokeratine." (PMID 31692820, 2019). "Immunohistochemical study showed the tumor cells were positive for smooth muscle actin (SMA) and beta-catenin, but negative for S-100 protein and CD34." (PMID 30223791, 2018). "All specimens demonstrated strong positive immunostaining for S-100 and GFAP proteins, whereas the tumor cells were not immunoreactive to DOG1, c-Kit (CD117), CD34, SMA and desmin." (PMID 30045739, 2018).
tumor (continued). "Immunohistochemical staining showed that the tumor cells were positive for CK, CK8/18, AFP, hepatocyte, GCP3, but negative for PLAP, CD10, CD30, CD34, and vimentin." (PMID 29351804, 2018). "In contrast, staining for alpha-SMA, cytokeratin (AE1/AE3), cytokeratin (CAM5.2), CK19, CD34, CD68, p63, S-100, Factor VIII, and desmin, CD56, chromogranin A, synaptophysin was all negative in the tumor cells." (PMID 30253798, 2018). "The tumor cells were diffusely positive for AFP, CK, CK8/18, GPC-3, and hepatocyte, but negative for CD30, CD34, CK19, D2–40, PLAP, and vimentin." (PMID 29351804, 2018). "It provides an alternative way to study the role of micro blood vessels and investigate their role in tumor progression and treatment response from public datasets, when the CD31/CD34 IHC stained images are not available." (PMID 29482496, 2018). "The tumor cells showed strong and diffuse nuclear immunostaining with beta catenin and were negative with STAT6, CD34 and bcl-2." (PMID 29168109, 2018). "The tumor showed positive immunostaining for Vimentin, CD31, CK7, D2–40, c-MYC, Ki67, focal positivity for PanCK, and negative immunostaining for Factor VIII, CD34, WT1, CK5/6, Calretinin, EMA, HBME-1, CEA, p63, EpCAM, Bcl-2, TTF1 and Thyroglobulin." (PMID 28810922, 2017). "The tumor cells showed generally positive for vimentin and negative for h-CALD, CD34, desmin, CD163, AE1/AE3, CK7 and CK20." (PMID 28320435, 2017). "On flow cytometric labeling, most of the tumor cells in the dogs with AML expressed CD45, CD18, and CD34 with aberrant negative expression of MHCII, as previously reported." (PMID 28620611, 2017). "Incisional biopsy of the gingival lesion displayed diffuse infiltration of undifferentiated tumor cells with granulocytic appearance, strongly immunopositive for CD99, myeloperoxidase and Ki-67 (60%), and negative for CD20, CD3, CD34 and TdT." (PMID 29075423, 2017). "Per report, the tumor exhibited weak and focal positivity for CD117 (KIT), vimentin and calretinen, and was negative for SMA, S100, CD34, and desmin." (PMID 28768491, 2017). "The PNET was CD56/CD34 positive CD45 negative, with a significant proportion of histiocytes and a minority of T lymphocytes among the tumor cells." (PMID 27567676, 2016). "The patient's bone marrow cells indicated clonal evolution of the tumor cells expressing CD13dim, CD33+, CD117+, and lacking HLA-DR, CD34 and CD11b." (PMID 27708545, 2016). "Immunohistochemically, the tumor cells express cytokeratin, calretinin, D2-40, thrombomodulin, and nuclear WT1 but are negative for Ber-EP4, CEA, CD15, and CD34." (PMID 27293940, 2016). "Of note would be the extensive expression of CD146 in the cytoplasm of most tumor cells as opposed to that of other vascular markers such as CD31, CD34, or smooth-muscle-actin." (PMID 26351605, 2015). "Immunohistochemical examination indicates that the tumor cells were diffusely positive for Factor VIII, Fli-1, CDK4, INI-1, MDM2, vimentin, focally positive for AE1/AE3, CD31 and negative for actin-sm, CD34, desmin, myoD1 and S-100." (PMID 26315812, 2015). "The pleomorphic tumor cells were strongly positive for desmin and focally positive for myoD1 but negative for myogen (Myf-4), CD117, CD34, and DOG1 IHC, suggesting rhabdomyosarcomatous differentiation." (PMID 25694839, 2015). "Immunohistochemically, the tumor cells of GISTs are positive for CD117 and CD34, but negative for FDC markers." (PMID 25435998, 2015). "Immunohistochemically, tumor cells were diffusely positive for Vimentin and CD99, focal positive for CD34, Bcl-2 and Actin, negative for CK, EMA, Desmin, CD117, GFAP, PR and S-100." (PMID 26155787, 2015).
tumor (continued). "Ultrasound guided core biopsy of the right breast revealed a spindle-cell neoplasm composed of tumor cells with blunt ended nuclei that were strongly positive for smooth muscle actin (SMA) and lacked expression of pan-cytokeratin, CD34, and S-100 (not shown)." (PMID 25469230, 2014). "Immunohistochemical staining revealed that the tumor cells were positive for AE1/AE3, cytokeratin (CK) 7, vimentin, cluster of differentiation (CD) 31 and E-cadherin, but showed no staining for CD10, CD34, factor VIII, CK20, carcinoembryonic antigen or desmin." (PMID 25120677, 2014). "Immunohistochemical (IHC) study showed that the tumor cells were positive for CD117, CD34, DOG-1, vimentin and S-100, while negative for desmin, smooth muscle actin and CK." (PMID 24527092, 2014). "In the present case, tumor cells were positive for SMA staining, but no immunoreactivity was observed for CD34, desmin or S-100." (PMID 24396463, 2014). "The tumor was positive for SMA and vimentin, and negative for desmin, S-100, CD34, pan-cytokeratin, and neuron-specific enolase." (PMID 25469230, 2014). "Immunohistochemical stains demonstrated that tumor cells were positive for smooth muscle actin (SMA) and calponin, and negative for S-100, CD34 and epithelial membrane antigen (EMA)." (PMID 25037940, 2014). "Regarding hematopoietic markers CD34 and CD45, all EWS samples showed negative expression in the tumor cells." (PMID 24498265, 2014). "By contrast, the tumor cells in the tumor described were negative for AFP, HepPar-1, K7, K19, CD34, CD56 and CD133, and positive for C-KIT and EpCAM." (PMID 25202388, 2014). "Recovery of CD34+ cells was reduced in EL4, but not EL4-v10 TB and IM7 contributed to a reduction in tumor-free and EL4-v10 TB mice." (PMID 24684724, 2014). "Immunohistochemical studies revealed that the tumor cells was positive for VIM and MDM2, and was negative for CK, MSA, SMA, DES, S-100 and CD34." (PMID 24444015, 2014). "In the present case, the epithelioid tumor cells were found to be positive for CD31, but negative for CD34 and factor VIII." (PMID 25120677, 2014). "The tumor cells were immunoreactive for CD10+, PR, and smooth muscle actin (SMA), but negative for desmin, S100, CD34, CD117, cytokeratins AE1AE3, CD68R, and ER." (PMID 24744931, 2014). "The cells of the tumor in the present study were positive for C-KIT, EpCAM and E-cadherin, but negative for other known HPC markers including AFP, K19, CD34, CD56, CD133 and albumin." (PMID 25202388, 2014). "In the present case, the tumor cells were positive for vimentin, CD68 and Ki-67, and negative for S-100, SMA, desmin, CD31, CD34, ALK and AE1/AE3." (PMID 24959221, 2014). "In the present case, immunohistochemistry revealed that the tumor was positive for GFAP, S-100 protein, vimentin, CD34, CD99 and D2-40 and negative for neuron markers (Syn and chromaffin protein/NeuN)." (PMID 24348765, 2014). "On a detailed immunohistochemical analysis, the tumor cells were intensely positive for smooth muscle actin (SMA), moderately positive for vimentin and negative for CD34 that was positive only in the vessels endothelium." (PMID 25408738, 2014). "Immunohistochemically, the tumor cells were positive for S-100 protein, vimentin and BCL-2, and negative for HMB45, Melan-A, CD117, CD34 and CD99." (PMID 25364450, 2014). "Immunohistochemistry the tumor was positive for vimentin, focal positivity with AE1-AE3 CK, CK5 and high molecular weight cytokeratin and negative for EMA, CD34, desmin, myosin, CroA, synaptophysin and S100." (PMID 23886403, 2013).
tumor (continued). "The medullary invasion by blasts (reflection of the tumor mass) of the total sample of CD34+, CD34+ CD38− patients and those not expressing CD34+ was respectively 79.4%, 81.25%, 83.3% and 74.8%." (PMID 23667721, 2013). "Immunohistochemical (IHC) analysis of the patient’s tumour revealed only focal SMA positivity, whereas tests for Desmin, Caldesmon, S100, CD34, EMA, and Pan-CK were negative." (PMID 24289252, 2013). "Immunohistologically, the tumor cells were immunoreactive for CD31 and CD34, but negative for cytokeratin, S-100, CD68 and factor VIII." (PMID 23759830, 2013). "Unlike LCA, the tumor cells in this case were negative for CD21 and FVIII antigen and positive for CD34 and CD8." (PMID 23984838, 2013). "The tumor cells were positive for CD117 and CD34, but negative for α-SMA, desmin and S-100 by immunohistochemistry." (PMID 23902675, 2013). "If tumor cells are not immunoreactive for either the S-100 protein or EMA, but are positive for vimentin, CD10, and CD34, these cells are considered to correspond to endoneurial fibroblasts." (PMID 24112233, 2013). "Immunohistochemical staining confirmed the tumor cells were strongly positive to Vim, SMA, MSA and negative to CD31, CD34." (PMID 24074285, 2013). "The negative activity of CK AE1/AE3, EMA, CD10, CK7, and CD34 and positive activity of HMB-45, Vimentin, and SMA of the tumour were consistent with epithelioid angiomyolipoma." (PMID 24490095, 2013). "The tumor cells were positive for smooth muscle actin (SMA), and negative for desmin, h-caldesmon, CD34, cytokeratin, S100 protein, and CD117." (PMID 23742153, 2013). "Immunohistochemistry has shown that non-adipocytic tumor cells are consistently positive for CD99 and, less frequently, for CD34 (75%) and Bcl-2 (60%)." (PMID 24179528, 2013). "In summary, the positive reactivity of CD34, Bcl-2, and SMA and negative reactivity of C-kit, S100, and desmin of the tumour were compatible with solitary fibrous tumour." (PMID 24490095, 2013). "The tumor size was 7.5×5 cm, and the immunohistochemical analysis revealed the tumor was positive for CD117, CD34 and DOG-1, but negative for S100." (PMID 23420084, 2013). "Immunohistochemically, the tumor was positive for CD31, CD34, and Vimentin, a mesenchymal marker, and negative for HAS and GPC-3, which excluded the possibility of hepatocyte origin." (PMID 22280556, 2012). "Immunohistochemically, tumor cells were positive for SMA, HMB45, and Melan-A and negative for CD10, RCC, CD45, CD117, CD34, EMA, and Desmin." (PMID 22953133, 2012). "Immunohistochemically, the tumor cells were widely positive for vimentin, CD56, CD99 and focally positive for synaptophysin, CD10, progesterone receptor, desmin and CD34, but negative for EMA, cytokeratin, estrogen receptor, S-100 and myoglobin." (PMID 23217062, 2012). "Immunohistochemically, the tumor cells were positive for vimentin, Ki-67, smooth muscle actin (SMA), and CD34, but negative for S-100." (PMID 23152982, 2012). "Immunohistochemically, the tumor cells were strongly positive for bcl-2 and CD99, partly positive for CK and EMA, and negative for CD117, CD34, SMA and desmin in all five cases." (PMID 22862905, 2012). "Immunohistochemically, the tumor cells showed positive for vimentin, while stains for CK, EMA, Calponin, CD34, AFP, hepatocyte and S-100 were all negative." (PMID 22221822, 2012). "IHC studies have shown that the tumor cells in DFSP contain vimentin and actin (focally and inconstantly) and CD34 (strongly and consistently), but they are negative for S100 protein, HMB-45, keratin, and FXIIIa." (PMID 23316399, 2012). "In our case, the preexisting tumor cells were positive for both SMA and CD34, while the tumor cells that metastasized were negative or weakly positive for SMA and negative for CD34." (PMID 23227375, 2012).